TPO (thyroid peroxidase)
Description:
Iodination and coupling of the hormonogenic tyrosines in thyroglobulin to yield the thyroid hormones T(3) and T(4).
Synonyms: TPX; MSA; TDH2A
Tractability: Small molecule: an approved drug acts on it; a high-quality ligand is known; it belongs to a druggable protein family. Antibody: its Gene Ontology location is reachable by antibodies, with high confidence; UniProt places it where antibodies can reach, with medium confidence; UniProt predicts a signal peptide or a membrane-spanning region. PROTAC: ubiquitination databases record sites on it; a small molecule that binds it is known.
Target class: Enzyme; Oxidoreductase
Safety:
Unwanted effects reported when the protein is acted on. In parentheses: how it was acted on, where the effect was seen, and who reports it.
Decrease, Population growth rate (inhibition; thyroid follicle; source: AOP-Wiki)
Increased Mortality (inhibition; thyroid follicle; source: AOP-Wiki)
Altered, Amphibian metamorphosis (inhibition; thyroid follicle; source: AOP-Wiki)
Cognitive Function, Decreased (inhibition; thyroid follicle; source: AOP-Wiki)
Increase, Adenomas/carcinomas (follicular cell) (inhibition; thyroid follicle; source: AOP-Wiki)
Gene: Protein-coding gene on chromosome 2 (1,373,933 to 1,543,711, forward strand). Ensembl gene ENSG00000115705.
Subcellular location: Membrane; Cell surface (Isoform 3)
Pathways (Reactome):
Metabolism: Thyroxine biosynthesis
Gene Ontology:
Molecular function: peroxidase activity; calcium ion binding; heme binding; iodide peroxidase activity
Biological process: embryonic hemopoiesis; cellular oxidant detoxification; response to oxidative stress; thyroid hormone generation
Cellular component: extracellular region; plasma membrane; cell surface; membrane
Genetic constraint (gnomAD): Loss-of-function variants: 78 observed, 97.23 expected, observed/expected ratio (o/e) 0.8, 90% interval 0.67 to 0.97. The upper end of that interval is the gene's LOEUF score, 0.97, which puts it in group 4 of 6, group 1 being the genes least tolerant of losing a copy. Missense variants: 1,225 observed, 1,256.9 expected, observed/expected ratio (o/e) 0.97, 90% interval 0.93 to 1.02. Synonymous variants: 538 observed, 526.46 expected, observed/expected ratio (o/e) 1.02, 90% interval 0.95 to 1.1.
Homologues: Orthologues: macaque TPO (95% identical), chimpanzee TPO (85% identical), rat Tpo (74% identical), mouse Tpo (73% identical), pig TPO (72% identical), dog TPO (69% identical), rabbit TPO (65% identical), tropical clawed frog tpo (51% identical), Drosophila melanogaster Pxd (22% identical), Drosophila melanogaster CG4009 (20% identical). Paralogues in human: PXDN (35% identical), EPX (34% identical), MPO (34% identical), LPO (32% identical), PXDNL (32% identical).
Diseases named in the same sentence as TPO in open-access papers:
TPO is named in the same sentence as 410 diseases in open-access papers, as found by Europe PMC text mining. Sharing a sentence is not in itself a finding about the gene and the disease. The quoted sentences say what the papers report.
hypothyroidism (397 papers, 2004 to 2026). Abnormally low levels of thyroid hormone. "In conclusion, our study elucidates a significant association between elevated anti-TPO antibody levels and renal dysfunction among elderly patients with hypothyroidism." (PMID 40937419, 2025). "There are three main mechanisms by which goitrogens cause hypothyroidism: blocking iodide uptake by the thyroid gland, interference with thyroid peroxidase enzyme activity, and blocking the functioning of deiodinase enzymes that convert T4 to T3." (PMID 40092044, 2025). "A statistically significant association was found between vitamin D levels and HT, hypothyroidism history, anti-TPO, anti-Tg, vitamin B12 level, and age (P < .05)." (PMID 41261692, 2025). "This study demonstrates that AITD is the predominant cause of hypothyroidism in our study subjects, with nearly 79% of patients showing anti-TPO antibody positivity." (PMID 41280993, 2025). "Pathogenic Mechanism: Vitamin D deficiency (25(OH)D <20 ng/mL) disrupts VDR-mediated Treg/Th17 balance, increasing anti-TPO titers by 40–60% and hypothyroidism progression risk." (PMID 40822954, 2025). "Homozygous or compound heterozygous variants in the TPO gene lead to a variable degree of iodine organification deficiency characterized by hypothyroidism with elevated thyroglobulin levels." (PMID 41262259, 2025). "For instance, iron deficiency impairs thyroid hormone synthesis by reducing thyroid-peroxidase activity and diminishing conversion of T4 to T3, which can lead to subclinical or overt hypothyroidism." (PMID 41007490, 2025). "further demonstrated that obesity was significantly associated with hypothyroidism, Hashimoto’s thyroiditis, and thyroid peroxidase antibodies, implying that prevention of obesity is crucial for reducing the burden of thyroid disorders." (PMID 40951428, 2025). "This study aimed to determine if patients with anti-TPO at GD diagnosis are more likely to relapse after ATD or RI treatment, and if patients with anti-TPO are at increased risk of developing hypothyroidism post-ATD treatment." (PMID 40255503, 2025). "Hashimoto’s thyroiditis (HT), an organ-specific autoimmune disorder characterized by lymphocytic infiltration and thyroid peroxidase (TPO) antibody production, has become the leading cause of hypothyroidism worldwide." (PMID 40822954, 2025). "She appeared to have been susceptible to autoimmune conditions, given her history of hypothyroidism with elevated thyroid peroxidase positive antibodies of 49.1 and an thyroglobulin antibody level of 208 (levels below 20 IU/mL are typically considered normal)." (PMID 40126291, 2025). "Using two different validation cohorts, we were able to show that the PRS outperformed an array of clinical hypothyroidism risk factors but also improved risk prediction beyond that of thyroid hormones and anti-TPO." (PMID 41238958, 2025). "Anti-TSH-R antibodies are commonly associated with orbital inflammation and hyperthyroidism, while anti-TPO antibodies are linked to thyrocyte destruction and hypothyroidism." (PMID 40978905, 2025). "Hashimoto’s disease, the most common cause of hypothyroidism, is diagnosed by the presence of anti-thyroid peroxidase and anti-thyroglobulin antibodies." (PMID 38883046, 2024). "Their research specifically demonstrated a greater risk of developing hypothyroidism in female SSc patients with the presence of anti-TPO antibodies." (PMID 38256549, 2024). "From study start, the prevalence increased in TS for hypothyroidism 40% to 58%, vitamin B12 deficiency 5% to 12%, celiac disease 4% to 7%, positive anti-TPO 26% to 41%, and antitransglutaminase antibodies 6% to 8% (P < .0001 vs controls)." (PMID 37758506, 2024). "Such pathological processes involve either autoantibodies to thyroid peroxidase (TPO-Ab) and thyroglobulin (Tg-Ab), leading to hypothyroidism, or TSH receptor autoantibodies (TSH-R Ab) causing hyperthyroidism." (PMID 39967901, 2024).
hypothyroidism (continued). "These autoantibodies mainly act on Thyroid peroxidase (TPO) and Thyroglobulin (Tg), resulting in atrophy and destruction of thyroid cells, even causing hypothyroidism." (PMID 39981137, 2024). "Anti-TPO antibodies were found in a significant number of people who had hypothyroidism, which supports the idea that these antibodies are linked to thyroid problems in autoimmune conditions." (PMID 39221289, 2024). "Both anti-TPO antibody and anti-Tg antibody were associated with an increased risk for hypothyroidism, with a weighted pooled RR of 1.92 (95% CI, 1.49-2.48; P<0.001) and 1.53 (95% CI, 1.40-1.88; P<0.001) respectively (Sup." (PMID 38972987, 2024). "Higher pre-operative TSH, older age, female sex, Hashimoto’s thyroiditis, autoantibodies anti-TPO and anti-Tg and right sided hemithyroidectomy were found to increase the risk of hypothyroidism post-operatively." (PMID 38972987, 2024). "At the end of the follow-up, hypothyroidism was significantly associated with the presence of anti-TPO antibody positivity, a small thyroid volume, and a hypoechoic pattern." (PMID 38256549, 2024). "HT is the primary cause of hypothyroidism and is characterized by positive thyroid peroxidase (TPO) antibodies (TPOAbs) and TGAbs." (PMID 39456701, 2024). "Several studies have identified risk factors for Li-induced hypothyroidism such as the thyroid peroxidase antibodies, female sex, older age, and a positive family history of hypothyroidism." (PMID 36672114, 2023). "In this study, we found that low titers of anti-TPO Abs were associated with hypothyroidism during treatment and after surgery, as well as with the remission rate." (PMID 37123800, 2023). "Those with goiter, progressively increasing TSH levels, and elevated thyroid peroxidase (TPO) antibodies are at greater risk for progression into over-hypothyroidism and should be considered for treatment." (PMID 37162766, 2023). "In summary, it seems likely that high titers of TPO antibodies are associated with residual symptoms in patients with hypothyroidism." (PMID 35966075, 2022). "Among other findings, women in the postpartum period (24–48 h) with positive anti-TPO had a five times greater risk of hypothyroidism." (PMID 35351167, 2022). "Iron deficiency due to low ferritin and hypochlorhydria in hypothyroidism decreases TPO activity and further impairs thyroid function." (PMID 36158423, 2022). "The risk of developing clinically overt hypothyroidism was correlated with anti-TPO antibody titers as follows." (PMID 36556267, 2022). "Many studies have documented an increased risk of GDM in hypothyroidism associated with high anti-TPO Ab titers during pregnancy." (PMID 35165548, 2022). "From the results of MESA and pathway analysis, we concluded that the anti-TPO antibodies positivity associated metabolic disorder contributed to hypothyroidism possibly through disturbance of amino acid metabolism in cord blood of pregnant women." (PMID 35331172, 2022). "The thyroid autoantibodies against thyroid peroxidase (TPO) and thyroglobulin (Tg) are the biochemical characteristics of Hashimoto’s thyroiditis, which is the most common cause of hypothyroidism." (PMID 35282438, 2022). "Choet al. found that preoperative TSH between 2.0 and 5.9 mIU/L, and two or more positive factors of Thyroglobulin, anti-thyroglobulin, and anti-thyroid peroxidase (anti-TPO) strongly increase the risk of developing postoperative hypothyroidism." (PMID 36636474, 2022). "In the multivariate logistic regression analysis, a positive TPO Ab status was associated with hypothyroidism in period 2 (adjusted OR: 4.78; 95% CI: 1.27–20.18; P = 0.024)." (PMID 35687484, 2022). "The results of this study suggested that fetal metabolic disorder is correlated with anti-TPO antibodies positivity, representing by abundance alteration of hypothyroidism associated metabolites and the related disturbance of amino acid metabolism pathways." (PMID 35331172, 2022).
hypothyroidism (continued). "A positive TPO Ab status in patients with Graves’ hyperthyroidism receiving the first administration of RAI is associated with a higher risk of early hypothyroidism." (PMID 35687484, 2022). "These mice show severe hypothyroidism and loss of Tshr, TPO, and Nis expression with signs of neoplastic alterations." (PMID 33176626, 2021). "The presence of autoantibodies against thyroid peroxidase causes there to be a 25–50% risk of subclinical hypothyroidism becoming overt hypothyroidism within 20 years." (PMID 33671229, 2021). "A significant body of evidence among T2DM patients suggests that increased age, gender (female), obesity, and thyroid peroxidase antibody positivity are associated with an increased risk of developing hypothyroidism." (PMID 34670571, 2021). "Because anti-TPO positive euthyroid women are under increased risk for developing hypothyroidism over time, some authors believe it is prudent to start levothyroxine treatment when TSH levels are above 2.5 mIU/L during pregnancy." (PMID 33874925, 2021). "Hypothyroidism due to autoimmune destruction is highly associated with centripetal obesity with metabolic derangements where both anti-TPO and anti-Tg positively correlate with serum triglyceride levels and waist circumference." (PMID 34772378, 2021). "Not surprisingly, our association of baseline and on treatment anti-Tg or anti-TPO antibodies with the development of hypothyroidism is supported by other anti-PD-1 studies." (PMID 33299547, 2020). "The most common cause of hypothyroidism is autoimmune disease, and a large number of studies have shown that TPO-Ab and TG-Ab are closely related to hypothyroidism." (PMID 32461982, 2020). "Congenital hypothyroidism–associated TPO mutations are usually biallelic; however, two siblings harbored a TPO mutation, which was definitively pathogenic (p.A397Pfs*76) but heterozygous, without an identifiable mutation on the other allele." (PMID 32765423, 2020). "A model combining TPO-Ab, TG-Ab, TG, and Fb can be used to screen populations at a high risk of developing hypothyroidism after radiotherapy." (PMID 32461982, 2020). "The univariate analysis demonstrated that sex, N-stage, and pretreatment TPO-Ab, TG-Ab, TG, and Fb counts were associated with hypothyroidism." (PMID 32461982, 2020). "The patients with overt hypothyroidism, cardiovascular risk factors, or positive TPO antibody, abnormal T4, and pregnant women were excluded from this study." (PMID 34466557, 2020). "Another study has shown a nuanced contribution (13%) of TPO-8/8 genotype with autoimmune thyroiditis risk, which is mainly associated with hypothyroidism." (PMID 32218930, 2020). "Sex, N-stage, antithyroid peroxidase antibody (TPO-Ab), antithyroglobulin antibody (TG-Ab), thyroglobulin (TG), and fibrinogen (Fb) were associated with hypothyroidism." (PMID 32461982, 2020). "Participants with lower TSH and TPO-Ab (-) show high rate of reversion to eu-thyroidism while higher TSH were independently associated with progression to overt hypothyroidism among elderly participants with SCH (≥65 years)." (PMID 33007021, 2020). "TPO-abs is, independently of Tg-abs, related to hyperthyroidism while Tg-abs is marginally associated with hypothyroidism at the presence of TPO-abs." (PMID 31791284, 2019). "A preoperative TOSH level of at least 2.2 μIU/ml, anti-TPO positivity, and lymphocytic infiltration of grade 3 or 4 were detected to be significantly associated with the development of hypothyroidism in univariate analysis." (PMID 31612123, 2019). "TPO-abs was significantly, independently of Tg-abs, associated with hyperthyroidism, while Tg-abs was marginally significantly related to hypothyroidism at the presence of TPO-abs." (PMID 31791284, 2019). "Treatment with only ibuprofen (p:0.039) and positive thyroid peroxidase antibody (anti-TPO) (p:0.029) were determined as the main risk factors for permanent hypothyroidism." (PMID 31729433, 2019).
hypothyroidism (continued). "Another study on iodine deficiency and hypothyroidism amongst pregnant women found 3.2% of the cases positive for antibodies to thyroid peroxidase and 18.5% of the women to have inadequate levels (<150 μg/L) of iodine." (PMID 33072977, 2019). "In sum, in a large well-defined BD population, we find that both TPO-abs and Tg-abs, instead of hypothyroidism or hyperthyroidism are significantly associated with RC, and such association is independent of thyroid dysfunction." (PMID 31791284, 2019). "The presence of goiter and elevated serum concentrations of anti-thyroglobulin antibody (TG-Ab) and anti-thyroid peroxidase antibody (TPO-Ab) at diagnosis or the progressive increase in serum TSH levels suggests an increased risk of hypothyroidism." (PMID 30356680, 2018). "The risk of hypothyroidism was higher in the individuals with anti-TPO antibodies of >60 U/ml than in those with anti-TPO-antibodies of <60 U/ml (8.5%, 128/1513 vs 5.3%, 591/11 059)." (PMID 29069397, 2018). "Epidemiological studies have shown that autoimmune pathologies against the thyroid gland, such as TPO Ab and Tg Ab (which cause hypothyroidism), often coexist with autoimmune pancreas disorders with islet lesions in cases of diagnosed type 1 diabetes." (PMID 30013597, 2018). "Some of the hypothyroidism loci had already previously been implicated in hypothyroidism through GWAS, including TPO, FOXE1, VAV3, and a variant in ATXN2 (rs597808) in high linkage disequilibrium (LD) with the R262W polymorphism in SH2B318." (PMID 30367059, 2018). "We found a tendency towards an association for TPO antibodies and hypothyroidism with disease activity." (PMID 29267515, 2017). "Both induced hypothyroidism and hyperthyroidism by autoimmune thyroid diseases have been associated with positive TPO level." (PMID 28637498, 2017). "In the present study, the association of preterm delivery with hypothyroidism and anti-TPO antibodies was evaluated." (PMID 30288165, 2017). "In patients with chronic hepatitis C (CHC), the thyroid disorders are characterized by an increased risk of ATD and hypothyroidism in females, elevated levels of anti-TPO antibodies, and by papillary thyroid cancer risk." (PMID 28751878, 2017). "When anti-thyroid peroxidase autoantibodies are present, there is a 25–50 % risk of subclinical hypothyroidism progressing to overt hypothyroidism within 20 years." (PMID 27761265, 2016). "The salient clinical manifestations of TPO gene mutation are permanent congenital hypothyroidism and goiter, with a variable degree of hypothyroidism and thyroid gland enlargement depending on the severity of the defect." (PMID 26761947, 2016). "Herein, we report on a novel compound heterozygous TPO mutation in a German-Thai patient with permanent congenital hypothyroidism who presented with a huge multinodular goiter necessitating surgical removal." (PMID 26761947, 2016). "Other reports about risk factors for hypothyroidism have also indicated links to anti-TPO antibodies, multinodular goiter, and preoperative thyrotoxicosis." (PMID 25918526, 2015). "The present investigation is aimed at screening the mutations/polymorphisms in TPO gene and their effects on the function of TPO gene leading to hypothyroidism in the population of West Bengal to establish the genetic etiology of the disease." (PMID 24829575, 2014). "We aimed to identify the spectrum of mutations in the TPO gene leading to hypothyroidism in the population of West Bengal to establish the genetic etiology of the disease." (PMID 24829575, 2014). "Our patient had an elevated level of TPO antibody indicating chronic autoimmune thyroiditis as the cause of his hypothyroidism." (PMID 24822067, 2014). "The FOXE1 gene has been previously associated with hypothyroidism and is known to regulate transcription of TPO." (PMID 24586183, 2014).